VIM (vimentin)
Diseases named in the same sentence as VIM in open-access papers (continued):
Sharing a sentence is not in itself a finding about the gene and the disease.
tumor (continued). "In addition, the immunohistochemistry assay showed the reduction of E-cadherin and the increased expression of Vimentin in BART13-3p stably over-expressed tumor tissues compared with control tumor tissues derived from the in vivo mouse models of NPC metastasis." (PMID 31907338, 2020). "In addition, the tumor may also be positive for Vimentin, α-inhibin, SMA, estrogen receptor and progesterone receptor." (PMID 33292402, 2020). "Importantly, IHC analysis of the serial sections showed that cancer cells from aggressive margins had higher levels of RNF38, vimentin and snail and loss of E-cadherin in both HCC and transplanted tumor tissues, strongly suggesting that cells with elevated RNF38 expression underwent EMT." (PMID 30836988, 2019). "EMT is usually associated with tumor initiation, malignant progression, cell migration, tumor metastasis, etc. and is often defined by downregulated expression of epithelial markers (such as E-cadherin) and increased expression of mesenchymal markers (such as N-cadherin and Vimentin)." (PMID 31429766, 2019). "HIF is indeed a catalyst for tumor progression fostering several pathways such as epithelial-mesenchymal transition (EMT), characterized by changes in cell morphology and cell-matrix adhesion with loss of E-cadherin and overexpression of fibronectin and vimentin fostering cellular detachment." (PMID 31903166, 2019). "Whether this ability of vimentin applies to tumor growth remains to be determined." (PMID 31126068, 2019). "PSS itself has no inhibitory effect on the growth of B16-F10 cells—however, it suppressed FGF2-mediated angiogenesis and invasion of B16-F10 cells, and also decreased the level of Vimentin, which might help enhance the sensitivity of tumor cells to chemotherapy." (PMID 31035725, 2019). "Moreover, the up‐regulation of miR‐539 or DLX1 gene silencing led to the inhibition of PCa cell proliferation, migration, invasion, EMT and tumour growth, accompanied by increased E‐cadherin expression and decreased expression of vimentin, Smad4, c‐Myc, Snail1 and SLUG." (PMID 31298493, 2019). "In addition, vimentin expression wasalso correlated to the largest tumor size (p<0.001)." (PMID 31038558, 2019). "Considering PD–L1 as a marker associated with immunotherapy response and immune escape in NSCLC and vimentin as marker of aggressiveness, we proposed that both PD–L1 and vimentin could be analyzed to refine tumor characterization and stratification at the early stage." (PMID 31546725, 2019). "Moreover, the level of Dock1, Snail, and Vimentin in the tumor xenograft were downregulated, but E-cadherin level was upregulated in the mice that was inoculated with SiDock1/MDA-MB-231 or miR-486-5p/MDA-MB-231 cells than Scr/ MDA-MB-231 or NC/MDA-MB-231 cells." (PMID 31528235, 2019). "The expression of vimentin in the ESCC cells was significantly upregulated, the expression of E-cadherin was significantly downregulated, and the invasion and migration of the ESCC cells were significantly enhanced after tumour-associated macrophages were added to the co-culture." (PMID 31186031, 2019). "Therefore, JAZF1 could promote GC tumour metastasis by promoting vimentin expression and suppressing E-cadherin expression via direct transcriptional repression." (PMID 31357957, 2019). "Thus, in themonolayer culture of tumor cells in the presence ofcytokine (104 U/mL), the expression of CK and EpCAMincreased by 50.5% and 47.8%, respectively, as comparedwith the control, but expression of vimentin was notobserved in this culture." (PMID 30930631, 2019). "Furthermore, expression of four proteins is associated with tumor progression/high risk AML: DOT1L, mTOR, VIM and ZNF521, whereas the expression of six proteins is associated with tumor suppression/low risk AML: AEBP2, CAST, CBFB, LSP1, MAP1S and probably PCBP1." (PMID 30634713, 2019).
tumor (continued). "TGF-β has been reported to function as a tumor promoter by inducing epithelial-to-mesenchymal transition (EMT), which features the loss of epithelial phenotypes (such as claudins and E-cadherin) and the acquisition of mesenchymal phenotypes (such as fibronectin, N-cadherin and vimentin)." (PMID 29568359, 2018). "The expression of vimentin, an important protein related to tumour metastasis, was downregulated, whereas that of E-cadherin was markedly elevated in sh-CCAL GC cells, suggesting that the change in these proteins may be involved in sh-CCAL-mediated malignant progression." (PMID 30250169, 2018). "Furthermore, it might be hard to find out the changes of vimentin in Eca109 because its expression is appreciable, which could be contribute to the poorly differentiated status of tumor cells." (PMID 29615660, 2018). "Vimentin and E-Cadherin had very different levels of expression in PDAC and normal pancreas as a consequence of epithelial-to-mesenchymal transitions (EMT) in malignant tissues as well as the presence of a dense tumor stroma, a desmoplastic reaction that is a hallmark of the PDAC microenvironment." (PMID 29993362, 2018). "Moreover, mRNA expression levels of miR-22-targeting genes and related downstream genes, MAPK1, Snail, Slug, N-cadherin, and vimentin were lower detected while E-cadherin were higher detected in tumor tissues from the miR-22 group compared to that in the NC group." (PMID 29434190, 2018). "A recent study reported that vimentin overexpression and the EMT were induced by PLAGL2 via Wnt/β-catenin signaling pathway in CRC, which stimulated the migration and invasion of tumor cells and may validate our findings that vimentin was related to lymph node metastasis in CRC." (PMID 29955607, 2018). "Likewise, these markers were also confirmed by immunohistochemical staining in serial sections of ICC tissues, and in the positive TRIM44 staining of ICC tissues, downregulaton of E‐cadherin and up‐regulation of vimentin, β‐catenin and snail were observed in invasive tumor fringe and vice versa." (PMID 29446253, 2018). "Although immunohistochemical detection of E-cadherin and vimentin protein expression in tumor samples is technically straightforward, the complexity of cancer genomes on one hand and of the EMT phenomenon on the other may require analysis of additional molecular parameters." (PMID 29472531, 2018). "As abnormal vimentin expression during the epithelial–mesenchymal transition has been regarded as an important element for epithelial plasticity and tumor metastasis, variation in the epithelial contribution to MD may obscure the relation between vimentin and MD." (PMID 30497427, 2018). "Additionally, an increase in E-cadherin expression in the CNE-2Z tumor may limit the propagation of EDA knockout tumors; while the decreased Vimentin in the SW480 tumor suggested impaired cell propagation." (PMID 29285230, 2017). "The EMT participates in tumor progression by increasing cancer cell motility, migration, invasion, and adhesion and is characterized by upregulation of mesenchymal proteins, such as vimentin, fibronectin, and N-cadherin, and downregulation of epithelial markers, such as E-cadherin." (PMID 29161296, 2017). "The number and size of the metastatic tumours also predominated in the HepG2-HBx group.The immunocytochemical result indicated that the epithelial marker of E-cadherin was down-regulated, whereas the mesenchymal marker of vimentin was up-regulated in the HBx overexpressed HepG2 cells." (PMID 29258558, 2017). "Furthermore, L1CAM expression was strongly associated with percentage of vimentin expressing tumor cells and expression of both L1CAM and vimentin indicated a subgroup with the highest change of recurrence, suggesting that L1CAM ascertains tumor aggressiveness, possibly through EMT." (PMID 29152102, 2017).
tumor (continued). "This ATM expression index was calculated by dividing average ATM pixel intensity within the pan-cytokeratin-positive malignant cell area by the average ATM pixel intensity within the corresponding vimentin-positive and pan-cytokeratin-negative tumour-associated stromal area." (PMID 28418844, 2017). "However, P6D4 stained positive for vimentin only in the tumours, indicating that these cells might be more prone to undergoing EMT in the presence of exogenous stimuli." (PMID 28094783, 2017). "Finally, EMA, D2-40, and vimentin positivity confirmed the meningeal nature of the tumor cells." (PMID 28860959, 2017). "However, the additional analyses of tumor samples from our and others’ cohorts supported the correlation of EGFR-mutation status with vimentin expression, suggesting that EGFR-mutation status may be prone to undergo EMT-mediated cancer cell dissemination." (PMID 28881820, 2017). "Tumour cells migration and invasion may be a consequence of vimentin overexpression." (PMID 28616237, 2017). "Notably, EMT has been recognized to be vital in promoting cancer metastasis, and c-Src has been demonstrated to play a crucial role in the induction of E-cadherin repressors and the vimentin promoter, which allows tumor cells to migrate/invade by activating downstream signaling pathways." (PMID 27078847, 2016). "Immunohistochemical staining for E-cadherin, Occludin, Vimentin, and N-cadherin showed that apigenin treatment increased E-cadherin and Occludin levels, whereas it decreased Vimentin and N-cadherin levels, in both the membranes and cytoplasm of tumor cells as compared to untreated cells." (PMID 27203387, 2016). "While vimentin, a type III intermediate filament protein forming the major cytoskeletal component of mesenchymal cells, is commonly used in diagnostic immunohistochemical panels, it is also expressed extensively in neoplasms of other lineages, making it an ineffective diagnostic marker." (PMID 27434038, 2016). "Interestingly, compared with the control cohort, the Barx2 knock-down cohort showed higher E-cadherin and lower vimentin expression in IHC staining of tumor xenografts, confirming our hypothesis that Barx2 acts as a cancer suppressor gene in GC." (PMID 27533254, 2016). "Increased vimentin expression could promote tumor angiogenesis and lymphangiogenesis." (PMID 26231404, 2015). "Finally, we found that the expression of several EMT markers correlated tightly with MCT2 expression in PCa tumours (r2 > 0.8), consistent with our observation of VIM and TGFB depletion in PCa cell lines following MCT2 knock-down and suggesting a link between MCT2 and EMT signalling pathways." (PMID 26035357, 2015). "Compartment specific analysis of protein expression will be accomplished by the use of compartment-specific stains (4′,6-diamidino-2-phenylindole (DAPI) for nuclei, pan-cytokeratin for tumour cells and the tumour cytoplasm, and vimentin for the non-malignant tumour-associated stroma)." (PMID 26156521, 2015). "AC-PDTXs retained the tumor epithelial component only at 1.5 months from the graft, whereas these xenografts showed only stromal tissue at 3 and 6 months from the graft as evidenced by microscopic (H&E staining) and immunohistochemistry (vimentin staining) analyses." (PMID 25785245, 2015). "In addition, especially in co-cultures of A549 cells an upregulation of vimentin could be observed suggesting an epithelial to mesenchymal transition (EMT) in tumour cells as previously reported." (PMID 24663399, 2014). "Taken together, the results from the present study suggest that the ability of resveratrol to inhibit tumor invasion is associated with the EMT, possibly by inhibiting the activation of the Hh signaling and regulating the expression of the important downstream EMT markers, E-cadherin and vimentin." (PMID 25069516, 2014). "In addition, E-cadherinlow/vimentin may be used as an indicator of tumor prognosis, whereby a small ratio indicates poor prognosis." (PMID 25120657, 2014).
tumor (continued). "In addition, all of these tumor types may express the epithelial marker, cytokeratin, in addition to endothelial markers and vimentin." (PMID 24932310, 2014). "In addition, we also used immunohistochemistry to evaluate the expression of Nodal, CD34 and Vimentin in HCC tumor tissues and investigated the association of Nodal expression with angiogenesis, EMT, clinicopathological characteristics, and prognosis." (PMID 24465741, 2014). "Additionally, Western blot analysis and immunofluorescence/immunoperoxidase staining showed that the deficiency of tuberin is associated with decreased expression N-cadherin and increased expression of vimentin in tumor tissues compared to control kidney tissue." (PMID 25149531, 2014). "The immunoreactivity of the representative EMT-associated markers, E-cadherin and vimentin, varied between the primary lung tumor tissues and the cancer cell nests in the effusions, indicating the presence of the EMT phenomenon in the primary lung tumors and MPEs during tumor progression." (PMID 23658677, 2013). "Thus, we hypothesize that the elevated expression of WDR66 in ESCC may promote EMT through an up-regulation of vimentin expression and a down regulation of occludin and cohesion of the tumor tissue." (PMID 23514407, 2013). "Since EMT and vimentin are also induced at epithelial wound edges, this raises the possibility that migration from the primary tumor could expose tumor cells to wounding stimuli that would only increase when CTCs enter the free-floating environment of the circulation." (PMID 24240660, 2013). "Interestingly, this gefitinib-resistant variant line (81B-Fb) consists of only fibroblast-like tumour cells and shows typical characteristics of EMT such as almost complete loss of E-cadherin, increased vimentin and snail expression and increased cell motility." (PMID 22315058, 2012). "Additionally, we stained mesenchymal human tumor cells for vimentin protein expression." (PMID 23110550, 2012). "Given the links between vimentin citrullination, inflammation, and cell proliferation, and given how important cytoskeletal integrity is for cell motility, we hypothesize that citrullination of vimentin by PAD enzymes may also affect tumor cell migration and promote an inflammatory microenvironment." (PMID 23019525, 2012). "In addition, increased expression of vimentin has also been found to localize on tumor neovasculature and this expression could also aide in the targeting or serve as a target in vimentin-directed cancer agents." (PMID 24212937, 2011). "However, as the majority of MM tumours express the protein this may be an explanation for the inducement of anti-vimentin antibodies observed in MM patients in this study." (PMID 22022619, 2011). "In the 3 cases where the proteomes of tumor cells freshly prepared from tumor nodules could be tested with autologous sera, two antigens, lamin B1 and vimentin, were detected with two of the tumor-serum combinations with otherwise heterogeneous antigenicity patterns." (PMID 20020065, 2009). "In tumour stroma and in control cores, inflammatory cells (macrophages, lymphocytes, granulocytes and plasma cells) and endothelial cells frequently showed positive staining for NF-κB p105, vimentin and Par6, whereas fibroblast-like cells only occasionally presented positive staining." (PMID 18854838, 2008). "In addition to the statistically significant clinical variables, tumour epithelial cell expression of NF-κB p105 (P=0.02), vimentin (P=0.001) and E-cadherin (P=0.03), and stromal cell expression of NF-κB p105 (P=0.001) and Par6 (P=0.0001) were prognostic indicators for DSS in univariate analyses." (PMID 18854838, 2008). "This hypothesis provides explanation for the phenotypic heterogeneity of these neoplasm and their variable IHC profiles taking into consideration the well-known inherent plasticity of the "vimentin+/CD34+ cell" to differentiate toward several mesenchymal lines." (PMID 16859566, 2006).
tumor (continued). "Immunohistochemistry is vital for establishing the diagnosis of LOT, as evidenced by tumor cell positivity for CK7 and PAX8 and negativity for CD117/KIT, vimentin, and CAIX." (PMID 41523983, 2026). "Individual cases exhibited variations, like higher vimentin with lower FAP and PECAM1/CD31, highlighting tumor morphological heterogeneity and regional adaptability." (PMID 40694103, 2026). "ARL4C knockdown increased epithelial marker E-cadherin while decreasing mesenchymal markers N-cadherin and Vimentin, indicative of EMT suppression and tumor-suppressive effects." (PMID 41328352, 2026). "Immunohistochemical analysis showed that tumor tissues treated with high doses of VER exhibited reduced levels of PCNA, Bcl-2, vimentin, MMP-2, p-AKT, and p-PI3K compared with the control group." (PMID 41158757, 2026). "In the murine xenograft model, SEA promoted tumor growth, increased the expression of Ki67 and Vimentin, and activated the MAPK and PI3K-AKT signaling pathways in tumor tissues." (PMID 41769997, 2026). "At the protein level, organoids expressed both stem/progenitor markers (nestin, vimentin, SOX10) and chromaffin differentiation markers (synaptophysin, CD56), although expression of the latter was markedly reduced compared to primary tumor tissue." (PMID 41928881, 2026). "The immunohistochemical results showed that the tumor was positive for PAX8, CA9 (diffuse box-like positivity), CK7, CD10, P504S, and vimentin." (PMID 41306531, 2025). "Between ARGs_High tumour cells and T cells, ITGB2-ICAM1 and TGFB1-TGFBR1 were ligand-receptor pairs with strong regulatory potential, while EDN1, JUNB, SOCS3, VIM and COL1A2 were top genes target to TGFB1." (PMID 40830065, 2025). "Based on these data, we propose that the SMR peptide and its analogs interact with specific amino acid sequences in Mortalin and Vimentin, thereby disrupting cellular processes essential for Epithelial–Mesenchymal Transition (EMT) and tumor progression." (PMID 41009417, 2025). "Real-time quantitative polymerase chain reaction analysis revealed a reduced expression of E-cadherin and an enhanced expression of vimentin, suggesting EMT suppression and the subsequent suppression of tumor aggressiveness following crizotinib administration." (PMID 40277792, 2025). "The EMT marker proteins, such as VIM, KRT18, KRT8, and MMP9 are involved in cell structure, motility, and matrix remodeling, which are crucial for tumor invasion and metastasis." (PMID 39858010, 2025). "During tumor progression, PBRM1 directly regulates vimentin expression, and PBRM1 deletion results in the activation of the EMT and subsequent metastasis." (PMID 40454484, 2025). "Regarding tumor capacity to grow, infiltrate and resist apoptosis after PDT, we assessed the expression of vimentin, nestin and SOX2 by immunofluorescence." (PMID 41009470, 2025). "In this context, the most extensively studied drug targeting vimentin intermediate filaments is withaferin A (WFA), a tumor inhibitor derived from the plant Withania somnifera." (PMID 39859358, 2025). "The co-expression of CK18 and vimentin indicated a partial EMT phenotype, reflecting tumor plasticity and adaptability to the in vivo microenvironment." (PMID 41472776, 2025). "For example, the EMT, mediated by factors like Vimentin (VIM), can work to create a tumor microenvironment that is difficult to target with conventional chemotherapy." (PMID 40282535, 2025). "This increased heterogeneity is likely attributable to spatially uneven EMT induction, as suggested by our analysis of vimentin-RFP reporter distribution, which revealed patchy regions of EMT activation across the tumor." (PMID 41415449, 2025).